ME1 (malic enzyme 1)
Diseases named in the same sentence as ME1 in open-access papers (continued):
Sharing a sentence is not in itself a finding about the gene and the disease.
cancer (continued). "The suppressive effect of ME1 inhibitor on cancer cell size in vitro is consistent with our previous work with the global Me1 hypomorphic null mouse in which we observed significant reductions in colon Mtor expression." (PMID 30250042, 2018). "We demonstrated that combining ME1 inhibition with glucose depletion synergistically inhibited cancer cell growth." (PMID 28481367, 2017). "In this study, we found that ME1 inhibition disrupted metabolism in cancer cells and inhibited cancer cell growth by inducing senescence or apoptosis." (PMID 28481367, 2017). "In this study, we explored the use of ME1 as a target of cancer treatment through testing the vulnerability of cancer cells to ME1 inhibition by analysing the resulting alterations in gene expression and metabolite levels." (PMID 28481367, 2017). "We found that most cancer cell lines express higher levels of ME1 than of ME2 and ME3, although some cell lines predominantly expressed ME2 and ME3." (PMID 28481367, 2017). "In glucose-restricted culture conditions, cancer cells increased ME1 expression, and tracer experiments with labelled glutamine revealed that the flux of ME1-derived pyruvate to citrate was enhanced." (PMID 28481367, 2017). "We demonstrated that ME1 inhibition induces metabolic reprogramming and abrogates redox balance in cancer cells, both being related to glucose metabolism." (PMID 28481367, 2017). "l-glutamine isotope profiling analysis revealed the metabolic alterations in cancer cells by ME1 knockdown." (PMID 28481367, 2017). "We demonstrated that ME1 knockdown increased the expression of HMOX-1 (HO-1), which is an oxidative stress marker regulated by Nrf2,18 suggesting that ME1 depletion disturbs metabolic and redox balance in cancer cells." (PMID 28481367, 2017). "In the TCA cycle, IDH1/2 and malic enzyme 1 (ME1), of which the levels are altered in many type of cancer cells, contribute to NADPH production." (PMID 26008980, 2015). "ME1 expression was found to be mutant KRAS associated in both a NSCLC mouse model and human NSCLC cancer cell lines." (PMID 26173780, 2015). "The results revealed significant differences in ME1 DNA methylation across 11 types of cancer." (PMID 40510340, 2025). "Therefore, this study aims to examine the fundamental expression, methylation levels, tumor mutation burden, immune microenvironment, tumor cell stemness, and immune-related functions of ME1 in a pan-cancer context through bioinformatics research." (PMID 40510340, 2025). "Given ME1’s established role in sustaining cancer cell survival under energy stress, its downregulation may impair tumor cell redox homeostasis and biosynthetic capacity, thereby limiting oncogenic progression." (PMID 40906080, 2025). "Additionally, ME1-driven glutaminolysis is associated with KRAS mutations, which are a metabolic phenotype associated with cancer stem cells (CSCs) and are emerging as a potential therapeutic target." (PMID 39996805, 2025). "Conversely, increasing ME1 expression enhanced these capacities, suggesting that ME1 may facilitate the proliferation and metastasis of tumor cells, thereby promoting cancer progression." (PMID 40510340, 2025). "Previous studies have demonstrated that ME1 functions as a cancer-promoting gene." (PMID 40510340, 2025). "Malic enzyme 1 (ME1) plays a key role in promoting malignant phenotypes in various types of cancer." (PMID 39996805, 2025). "miRNAs targeting ME1 have shown potential in suppressing cancer progression." (PMID 39996805, 2025). "ME1 also promotes cancer cell proliferation under hypoxic conditions." (PMID 39996805, 2025). "Moreover, tumor budding is significantly correlated with ME1 expression, with ME1 levels increasing with cancer progression." (PMID 39996805, 2025). "As a result, ME1 promotes the malignant phenotypes of cancer cells and poor patient prognosis." (PMID 39996805, 2025). "We analyzed the ME1 expression levels in both normal and tumor tissues across various cancer types." (PMID 40510340, 2025).
cancer (continued). "ME1 is strongly associated with EMT, which is accompanied by enhanced stemness in cancer cells." (PMID 39996805, 2025). "Different findings confirm a key function of ME1 in liver, adipose tissue, and in cancer cells." (PMID 39335602, 2024). "However, they also found an adaptability of cancer cells to ME1 silencing after long culture periods." (PMID 36612292, 2022). "In addition, in our study, the correlation between tumor budding and ME1 expression increased with the progression of cancer, suggesting that ME1 strongly promotes tumor budding and the malignant phenotype in OSCCs." (PMID 32998265, 2020). "Higher level of ME1 was shown to regulate glucose metabolism and protect cancer cell apoptosis." (PMID 31315616, 2019). "Furthermore, ME1 is used as prognostic and predictive marker for radiotherapy in cancer suggesting a critical role in metabolic reprogramming of cancer cells." (PMID 31881713, 2019). "In cancers, ME1 is active enough to provide sufficient level of reductive power for lipid biosynthesis and de novo synthesis of cellular phospholipids may be sustained even if the glycolytic generation of NADPH is shut down." (PMID 29958416, 2018). "Moreover, ME1 abundance in some cancer cells was reported to be a prognostic marker for efficacy of radiation therapy." (PMID 30250042, 2018). "ME1 expression is upregulated in human cancers, such as nasopharyngeal carcinoma and neuroblastoma." (PMID 30425310, 2018). "Moreover, our in vitro experiments utilizing two human CRC cell lines confirmed that ME1 is important for cancer cell growth (hyperplasia and hypertrophy)." (PMID 30250042, 2018). "ME1 contributes to the cytoplasmic pool of NADPH, a fraction of which is used by Fatty Acid Synthase (FASN), a primary lipogenic enzyme that is upregulated in many cancers and is itself implicated in tumor genesis and metastasis." (PMID 30250042, 2018). "Several lines of evidence link ME1 to regulation of cancer cell growth." (PMID 30250042, 2018). "In addition, cancer cells showed higher sensitivity to ME1 depletion in glucose-restricted conditions compared to normal culture conditions." (PMID 28481367, 2017). "Our data demonstrate that ME1 is a promising target for cancer treatment, and a strategy using ME1 inhibitors combined with inhibition of glycolysis, PPP or redox balance regulators may provide an effective therapeutic option." (PMID 28481367, 2017). "We need further studies to identify cell fate determinants in ME1-suppressed cancer cells, which could be sensitivity markers for a ME1 inhibitor in clinical settings." (PMID 28481367, 2017). "Taken together, these findings suggest that ME1 has an important function in the growth and survival of cancer cells and that it could be a target for cancer therapy." (PMID 28481367, 2017). "From these results, we speculated that ME1 inhibition would synergistically inhibit cancer cell growth in glucose-depleted conditions." (PMID 28481367, 2017). "Taken together, our results demonstrate that ME1 inhibition suppresses cancer cell growth and induces apoptosis or senescence depending on the cellular context, consistent with previous reports, and that tumours in a nutrient-limited microenvironment are a sensitive target for ME1 inhibition." (PMID 28481367, 2017). "We speculate that ME1 depletion suppresses cancer cell growth by abrogating metabolic and redox balance in the cancer cells, and the specific phenotype such as senescence, apoptosis, or others, depends on cellular context in each cell line." (PMID 28481367, 2017). "Along with ME1-mediated reprogramming of energy metabolism, extracellular carbonic anhydrase and monocarboxylate transporters play key roles in decreasing the extracellular pH under hypoxic conditions, further promoting cancer cell invasion, metastasis, and stemness." (PMID 39996805, 2025).
cancer (continued). "This suggests that the deregulation of ME1 expression may be implicated in various cancers and is unlikely to be attributed to technical artifacts, randomness, or bias in the sample identification standards within the database." (PMID 40510340, 2025). "Therefore, ME1 knockdown is linked to oxidative stress and NADPH decrease in cancer patients." (PMID 39335602, 2024). "The fact that ME1 was found to be more important in supporting cancer survival in vivo and under low glucose conditions could be explained by the fact that ME1 being a cytosolic enzyme would be able to supply pyruvate to fuel OXPHOS without disturbing mitochondrial activity." (PMID 34932167, 2021). "Targeting of ME1 may add to the armentarium of therapies for cancers of the gastrointestinal tract." (PMID 30250042, 2018). "Therefore, we examined the effects of ME1 inhibition on cancer cell proliferation and metabolism." (PMID 28481367, 2017). "However, pyruvate (m+3) and citrate (m+6) were observed only in cells cultured in glucose-free media, suggesting that ME1 activity could be induced in cancer cells under glucose-depleted condition." (PMID 28481367, 2017). "ME1, G6PD, and IDH1 all play important roles in metabolic pathways that are often altered in cancer cells to support their rapid growth and proliferation." (PMID 39996805, 2025). "When deprived of sugar, both glycolysis and the PPP were inhibited, leading to the enhanced ability of several cancer cells to upregulate the expression of ME1 for pyruvate synthesis and NADPH production and increased sensitivity to ME1 ablation." (PMID 39061847, 2024). "Another candidate is malic enzyme 1 (ME1), which scaffolds 6PGD in U2OS cancer cells, forming a hetero-oligomer of ∼150 kDa and enhancing its binding with 6-phosphogluconate." (PMID 39373581, 2024). "Malic enzyme 1(ME1) is frequently overexpressed in cancers, and catalyzes the reversible oxidative decarboxylation of malate to pyruvate, yielding NADPH from NADP+, ME1 as a major cytoplasmic source of NADPH." (PMID 37580393, 2023). "ME-1 has significant effects on cancer metabolism because NADPH is necessary for anaerobic respiration, and ME-1 level is found to be high in some cancers." (PMID 35958818, 2022). "Similar results confirming the role of ME1 under low glucose conditions were obtained on human cervical HeLa and large cell lung NCI–H460 cancer cells." (PMID 34932167, 2021). "NRF2 plays a key role in tumorigenesis since it is usually upregulated in several cancer types triggering in turn upregulation of its target genes such as G6PD, malic enzyme 1 (ME1), and isocitrate dehydrogenase 1 (IDH1)." (PMID 34572981, 2021). "Under these conditions, ME1 alone was able to account for the necessary NADPH and increase cancer cell survival." (PMID 34932167, 2021). "Interestingly, ME1 expression in KP-/-C mouse and human PDAC tumors and organoids mimics that of PC in that it is more highly expressed in cancer cells compared to stroma, suggesting that ME1 could also contribute to the higher pyruvate carboxylation seen in cancer cells compared to PSCs." (PMID 32648540, 2020). "Malic enzyme 1 (ME1) regulates one of the main pathways that provide nicotinamide adenine dinucleotide phosphate (NADPH), which is essential for cancer cell growth through maintenance of redox balance and biosynthesis processes in the cytoplasm." (PMID 28481367, 2017). "Cancer cells regulate NADPH homeostasis through multiple pathways such as the PPP and the flux through ME1 and IDH1 in the cytoplasm." (PMID 28481367, 2017). "Enzymes utilized for glutamine metabolism in PDA, GLS1, GOT1/2, and malic enzyme 1 (ME1) (see pathway), in addition to NQO1, were significantly upregulated in PDA compared to 17 other cancers when assessed using the Oncomine webtool." (PMID 26462257, 2015).
cancer (continued). "The KEGG pathway analysis results indicated that among 26 genes some of them were found to have roles in cancer related pathways like cell cycle (MCM2), Jak-STAT (SOCS1), MAPK (STMN1), PPAR signaling pathways (ME1)." (PMID 25978727, 2015). "The decrease in leptin:adiponectin ratios in MOD-1 and SPI-HF-fed WT mice, compared to CAS-HF- fed WT mice, further substantiates the linkage between the cancer-preventive effects of SPI consumption and reduction in ME1 expression." (PMID 23056418, 2012). "Rather than acting as an independent cancer promoter, ME1 works in conjunction with lipid metabolism, cell proliferation, cell motility promotion, ROS generation related to EMT, NADP recycling enzymes, and redox networks." (PMID 39996805, 2025). "To investigate the differential expression of ME1 across various human cancers and their corresponding paracancerous tissues, we utilized the TIMER2.0 platform to analyze RNA sequencing data from 33 cancers within The Cancer Genome Atlas (TCGA)." (PMID 40510340, 2025). "Indeed, ME1 has been found increased in different kinds of cancers as well as IDH1 and glucose-6-phosphate-dehydrogenase (G6PD), likely preserving cancer cells from excessive reactive oxygen species (ROS) levels and in turn damage to molecules and apoptosis." (PMID 39335602, 2024). "Indeed, downregulation of several glycolysis genes deeply involved in cancer progression (ENO1, ME1, SLC2A4RG, PFKL and DLAT) was confirmed by RT-qPCR in siRNF40-treated HCC1806 cells." (PMID 37770435, 2023). "The expression of ME1 was not significantly different in sorted cancer cells compared to the whole tumor (p=0.1114), but was significantly higher in sorted cancer cells compared to fibroblasts (p=0.0009) based on unpaired, two-tailed student’s t-tests." (PMID 32648540, 2020). "Pre-clinical studies targeting ME1 have shown positive effects on cancer cells, but as far as we know, no clinical therapy targeting inhibit ME1 have yet been approved." (PMID 29805774, 2018). "We also showed that, in glucose-depleted conditions, cancer cells become dependent on the ME1 flux to produce NADPH and pyruvate and to manage redox homeostasis, suggesting that these cells become vulnerable to reduced ME1 activity." (PMID 28481367, 2017). "The ME1 knockdown experiments described here revealed that ME1 depletion does not induce acute cell growth inhibition, but suppresses cancer cell growth gradually by inducing senescence in HCT116 and PC3 cell lines or apoptosis in H460 cell line." (PMID 28481367, 2017). "Therefore, serine-mediated one-carbon metabolism compensates for G6PD loss in KL cancer cell survival, although this does not preclude the potential compensatory cytosolic NADPH production through ME1 or IDH1." (PMID 38997257, 2024). "In addition, oxPPP dysfunction induces ME1 and IDH1 flux to generate NADPH from glutaminolysis, but folate‐mediated 1C metabolism cannot function because of dihydrofolate reductase dysfunction in G6P knockout cancer cells." (PMID 35534945, 2022). "However, only ME1 and ME2 were considered to play a role in cancer metabolism." (PMID 34932167, 2021). "Thus, we tested whether malic enzyme activity could sustain M+1 labeling of aspartate in PDAC cancer cells lacking PC by using CRISPR/Cas9 to knock out malic enzyme 1 (ME1)." (PMID 32648540, 2020). "Importantly, we found that growth of cancer cells was highly sensitive to inhibition of ME1 enzyme activity; by contrast, growth of non-tumorigenic intestinal epithelial cells (IEC6) was relatively resistant to ME1 inhibition albeit sensitive to Wnt pathway inhibition." (PMID 30250042, 2018).
cancer (continued). "Our analysis revealed that ME1 expression exhibits both positive and negative correlations with TMB, MSI, and tumor stemness status, with variations observed across different cancer types." (PMID 40510340, 2025). "Genes involved in the glutamine-dependent transamination pathway (GLS1, GOT1/2, ME1) and NQO1, but not GLUD1, are highly expressed in PDA relative to other cancers." (PMID 26462257, 2015). "ME1 expression did not decreased in glucose-depleted conditions, although the levels of other NADPH-producing enzymes decreased, which suggests that cancer cells depend in part on ME1 in glucose-depleted conditions." (PMID 28481367, 2017).